INS (insulin)
Diseases named in the same sentence as INS in open-access papers (continued):
Sharing a sentence is not in itself a finding about the gene and the disease.
pancreatitis (150 papers, 2009 to 2026). Inflammation of the pancreas. "Pembrolizumab-associated HTG-causing pancreatitis can be successfully managed with insulin therapy to lower serum TG levels." (PMID 40432658, 2025). "This case highlights the importance of individualised risk–benefit consideration when initiating insulin infusions outside the setting of pancreatitis, particularly to avoid complications such as hypoglycaemia." (PMID 40701175, 2025). "There was no clear association between initial level of HTG and presence of pancreatitis, age, or IV insulin requirement in our described cases." (PMID 40612706, 2025). "Our study also found an increased incidence risk of pancreatitis in the GLP‐1 RAs group when compared to both insulin and metformin groups." (PMID 39435881, 2024). "The circulating abundances of ten candidate miRNAs implicated in the regulation of insulin production and pancreatitis risk were analyzed in relation to MRI-determined IPFD and MRS-determined liver fat percentage." (PMID 37762694, 2023). "Our analysis showed that age, family history of PDAC, pancreatitis/cholecystitis, weight loss, and rapid increase in glycemia/necessity of insulin are robust candidates." (PMID 36230607, 2022). "Loss of insulin secretion (Ins2Akita mice) or loss of acinar IRs (PACIRKO mice) makes pancreatitis worse." (PMID 34282152, 2021). "Our case report explains how well insulin works in stable patients with severe pancreatitis and thus prevents associated morbidity and mortality." (PMID 33815980, 2021). "Reduced PMV is associated with increased SMFD and decreased insulin sensitivity in individuals after pancreatitis." (PMID 32630360, 2020). "In the pancreas, low pHi plays an important role in glucose-induced insulin release, while low [Mg2+]i is associated with decreased insulin secretion and pancreatitis." (PMID 29706896, 2018). "Severe HTG can be associated with pancreatitis and this may require additional IV insulin therapy delaying transition to subcutaneous insulin." (PMID 40612706, 2025). "Consequently, insulin's multifaceted mechanism of action can mitigate the risk of pancreatitis more effectively than plasmapheresis, despite the latter's rapid triglyceride clearance." (PMID 39958046, 2025). "L-asparaginase can directly inhibit insulin biosynthesis, causing impaired intracellular signaling, reducing and modifying insulin receptors, and indirectly reducing insulin production via induction of pancreatitis and beta cells destruction." (PMID 35743665, 2022). "Future studies may benefit from employing it in exploring the associations between IPFD and insulin traits in the post-pancreatitis setting." (PMID 32967240, 2020). "However, it is known that L‐arginine stimulates the release of insulin and causes necrotic pancreatitis with specific elevation of amylase in serum and urine." (PMID 28971613, 2017). "Of all its potential causes (including pancreatitis), insulin injections are among the rarest ones." (PMID 25298886, 2014). "Adjustments for medication potentially associated with pancreatitis and insulin use resulted in a higher risk of acute pancreatitis, which may be an indicator of disease severity; however, further study is warranted to better understand this observation." (PMID 22416857, 2012). "Concomitantly, the HFMD mice had significantly decreased insulin expression and number of islets in the pancreas, showed histological characteristics and phenotypes of mild pancreatitis, which may underlie the observed loss of insulin production and increased blood glucose levels." (PMID 36978130, 2023). "Finally, exogenously administered insulin using the hyperinsulinaemic euglycaemic clamp significantly attenuated caerulein infusion induced pancreatic injury associated with the early phase of pancreatitis." (PMID 34282152, 2021).
pancreatitis (continued). "However, infected mice (both RD and HFD mice) had a decreased glucose tolerance compared to uninfected mice, which agrees with our previous report that T. cruzi infection causes pancreatitis and deregulated insulin signaling that persists into the stage of chronic infection." (PMID 31949545, 2019). "Combined insulin and heparin therapy has demonstrated efficacy in rapidly lowering TG levels in hyperlipidemic pancreatitis." (PMID 40937420, 2025). "In this study, it was proven for the first time that even electrons can lead to characteristic signs of radiation-induced pancreatitis, the degree of which was assessed based on the levels of insulin, glucose, and amylase." (PMID 40508047, 2025). "Tirzepatide appears to mitigate these effects by enhancing insulin sensitivity and promoting cellular repair, potentially counteracting damage from conditions like pancreatitis." (PMID 41116319, 2025). "This disruption can lead to altered insulin secretion and contribute to beta cell dysfunction, which is particularly relevant in the context of pancreatitis and other pancreatic disorders." (PMID 39948335, 2025). "For example, one randomized controlled trial indicated that although plasmapheresis cleared triglycerides more quickly, patients treated with insulin had a lower incidence of progression to severe pancreatitis and persistent organ failure." (PMID 39958046, 2025). "More research is necessary for the use of early TPE in insulin-resistant cases of HTG to prevent impending pancreatitis." (PMID 41393592, 2025). "Is low-molecular-weight heparin combined with insulin superior to insulin alone in improving clinical outcomes in hypertriglyceridemic pancreatitis?" (PMID 41201803, 2025). "used continuous infusions of insulin and heparin in patients with hyperlipidemic pancreatitis and observed rapid declines in TG levels." (PMID 40937420, 2025). "The dose and regimen of insulin should be individually adjusted based on the patient’s blood glucose levels and the severity of pancreatitis." (PMID 40937420, 2025). "According to a meta‐analysis of 12 randomized clinical trials, the risk of pancreatitis, cholecystitis, MACE‐4 and neoplasms following tirzepatide treatment appears to be comparable to GLP‐1 receptor agonists, placebo or insulin." (PMID 40555920, 2025). "It emphasizes the preferential use of enteral nutrition over total parenteral nutrition (TPN), alongside aggressive yet balanced fluid and insulin therapy aimed at resolving both pancreatitis and the metabolic crisis." (PMID 41262426, 2025). "Common risk factors include dehydration, pregnancy, prolonged fasting, pancreatitis, abuse of cocaine, infections, bariatric surgery, liver cirrhosis, gastroparesis, insulin pump malfunction, and glycogen storage disorders." (PMID 40357083, 2025). "He remained fasting on bowel rest to manage pancreatitis, so IV insulin infusion was continued to maintain tight glycemic control until hospital day 9 when feeds resumed." (PMID 40612706, 2025). "Our sample-focused analysis followed a triad of turning points between the pancreas and parathyroid with the confirmation of primary hyperparathyroidism: hypercalcemia-linked pancreatitis, MEN1 gene pathogenic variants, and insulin resistance." (PMID 38928056, 2024). "Comment: In HTG-induced AP, additional treatments beyond standard pancreatitis therapy include the administration of insulin and/or heparin, and plasmapheresis." (PMID 39599919, 2024). "GPx1 knockout mice exhibit mild pancreatitis substantiated by diminished β cell mass, mild impairment of insulin secretion, and decreased fasting insulin levels (Brigelius-Flohé and Flohé 2020)." (PMID 38483584, 2024). "Others reported that this calcium exporter can mediate pancreatitis responses and contribute to insulin’s beneficial effects in acute pancreatitis." (PMID 39010833, 2024).
pancreatitis (continued). "For liraglutide, substantially increased incidence risks of pancreatitis, acute nephritis, thyroid cancer, thyroid dysfunction, and leukemia were observed in comparison to both insulin and metformin groups." (PMID 39435881, 2024). "The case also explores the potential for insulin as a first-line treatment in HTG-induced pancreatitis over plasmapheresis, contributing to evolving guidelines." (PMID 38707179, 2024). "This increase in severity of pancreatitis in Ins2Akita and PACIRKO mice was due to a loss of insulin-induced Akt-mediated phosphorylation of PFKFB2, which normally preserves glycolytic ATP supply to PMCA and prevents cytotoxic Ca2+ overload." (PMID 34282152, 2021). "We subcutaneously administered a single dose of insulin (2 IU/kg) in 5% glucose 3 hours after pancreatitis induction." (PMID 33491670, 2021). "Using cellular models of pancreatitis our previous studies revealed that insulin protects acinar cells from cellular injury." (PMID 34282152, 2021). "We next wanted to determine the specific molecular mechanism for the protective effects of insulin on acinar cells during pancreatitis." (PMID 34282152, 2021). "Ins2Akita mice exhibit no signs of collateral injury or inflammation of neighbouring cells of the islets (insulitis) or adjacent acinar cells making this strain a good model for studying the effects of impaired insulin secretion on pancreatitis." (PMID 34282152, 2021). "The present study also showed, using cellular models of pancreatitis, that insulin signalling protects against POA-induced ATP depletion, inhibition of the PMCA and the consequent cytotoxic Ca2+ overload." (PMID 34282152, 2021). "Similar results were obtained in an l-arginine-induced rat model wherein no change in alpha and beta cell counts but a significant decrease in insulin secretion was observed 1 month after the induction of pancreatitis." (PMID 34566890, 2021). "Among non-insulin antidiabetics, DPP-4is are associated with higher AEs reporting of the gastrointestinal tract, pancreatitis, malignancies, infection, musculoskeletal system, general disorders, hypersensitivity and skin, corroborating clinical trial evidence." (PMID 32938499, 2020). "Insulin secretion was decreased in pancreatitis/CF patient-derived pancreas-on-a-chip by 7.9%, but it was not significant." (PMID 31311920, 2019). "Experimental data suggest that insulin has a local protective effect on acinar cells during pancreatitis." (PMID 31620021, 2019). "Although heparin and insulin have been used, plasmapheresis and lipid apheresis are becoming more popular management options for hyperlipidemic pancreatitis." (PMID 30648042, 2018). "Dengue viruses inducing a transient pancreatitis or insulin resistance during the viremic phase are possible mechanisms." (PMID 29078811, 2017). "Some of the causes that have been reported to induce euglycemic DKA include low caloric intake and starvation or prolonged vomiting, pregnancy, pancreatitis, insulin pump use, and SGLT2 inhibitors." (PMID 27579186, 2016). "They found β-galactosidase/insulin double-positive cells in islets in a pancreatitis model, with a distribution that was very similar to that of the EGFP/insulin double-positive cells described here." (PMID 27526291, 2016). "Collectively these data provide evidence that insulin protects the PMCA from inhibition by pancreatitis-inducing agents such as POA." (PMID 24993827, 2014). "Significance: This provides an important therapeutic strategy for treating pancreatitis with insulin therapy." (PMID 24993827, 2014). "The aim of the current study was to test the protective effects of insulin on cellular injury induced by the pancreatitis-inducing agents, ethanol, POA, and POAEE." (PMID 24993827, 2014). "This analysis revealed reports of pancreatitis in patients using acarbose, chlorpropamide, exenatide, glimepiride, glipizide, insulin, metformin, miglitol, nateglinide, pioglitazone, pramlintide, repaglinide and rosiglitazone." (PMID 20412332, 2010).
pancreatitis (continued). "Likewise, the pancreas is a vital metabolic organ responsible for maintaining glucose homeostasis through the secretion of insulin, glucagon and a variety of digestive enzymes; heightened SUV levels in the pancreas are linked to pancreatitis." (PMID 39189415, 2024). "Furthermore, the patient's management involved insulin therapy for DKA and HTG-induced acute pancreatitis, deferring plasmapheresis and anticoagulation due to the risk of hemorrhagic transformation in pancreatitis." (PMID 38707179, 2024). "We used basal insulin as an active comparator while accounting for major confounding factors and time-related biases, as well as adjusting for treatment with other GLMs and history of pancreatitis." (PMID 38175642, 2024). "Additionally, the inhibition of Eph receptors in pancreatic neuroendocrine tumors has been shown to reduce insulin secretion, making them a potential therapeutic target." (PMID 39839790, 2024). "Causal associations between pancreatitis and fasting glucose, HbA1c and fasting insulin were also not observed in the present study." (PMID 36999014, 2023). "The reason may be that uric acid, as a pro-inflammatory factor, may aggravate the inflammatory response in patients with pancreatitis, thus affecting the secretion of insulin by islet cells." (PMID 37501096, 2023). "The vitamin status of an individual may affect insulin traits and glycaemic control; therefore, future studies should investigate vitamin levels in a post-pancreatitis population using more advanced assessment methods." (PMID 35406092, 2022). "However, once insulin secretory capacity becomes markedly depleted due to glucose toxicity or pancreatitis, it is usually difficult to withdraw from insulin therapy." (PMID 35029244, 2022). "To investigate this further we next tested whether insulin treatment was sufficient to preserve glycolytic flux during pancreatitis." (PMID 34282152, 2021). "To test whether endogenous insulin had any protective effect during AP, we first induced experimental pancreatitis in parallel groups of age-matched type-1 diabetic Ins2Akita mice vs control C57BL/6 wildtype mice (WT)." (PMID 34282152, 2021). "Therefore, phosphorylation of PFKFB2 acts as a ‘volume control’ for glycolytic flux and thus ATP production and is thus likely to be the major molecular mechanism for the protective effects of insulin during pancreatitis." (PMID 34282152, 2021). "Moreover, this diabetic-induced severe pancreatitis phenotype was partially corrected by exogenous administration of insulin." (PMID 34282152, 2021). "To further consolidate the possibility that CFTR function directly affects insulin secretion, we examined the cell–cell functional correlation between PDECs and islet cells derived from pancreatitis/CF patient, who was diagnosed with very mild CF and underwent TPIAT." (PMID 31311920, 2019). "Second, even after adjustment, there were still significant differences in the characteristics of the high-dose and non-high-dose corticosteroid groups, such as in the rates of pneumonia, pancreatitis, lung and abdominal trauma, neurological dysfunction and insulin." (PMID 29415701, 2018). "However, the current study provides the first evidence that insulin directly protects acinar cells againist bona fide pancreatitis-inducing agents in cellular models of the disease." (PMID 24993827, 2014). "In l-arginine-induced pancreatitis, acinar cells surrounding the islets of Langerhans remain relatively intact compared with distal injured acinar cells suggesting a paracrine protective role for insulin." (PMID 24993827, 2014). "Although these findings are novel, several lines of evidence from animal studies and human clinical studies suggest that insulin might have a protective role during pancreatitis (9, 12, 13, 16, 18, –, 21, 36, –, 43)." (PMID 24993827, 2014).
pancreatitis (continued). "Because POA appeared to be the most cytotoxic pancreatitis-inducing agent tested, we next wanted to test whether insulin pre-incubation would prevent this POA-induced [Ca2+]i overload." (PMID 24993827, 2014). "Evidence suggests that insulin may ameliorate the course of clinical acute pancreatitis (9, –, 11) and protect against experimentally induced pancreatitis (12, –, 16)." (PMID 24993827, 2014). "Notably, pancreatitis (sHR: 2.12, 95% CI: 1.14–3.95) and leukemia (sHR: 6.88, 95% CI: 2.06–22.94) were exclusively associated with long‐term GLP‐RAs (>12 months) usage when compared with the insulin group." (PMID 39435881, 2024). "Therefore, fatty infiltration of the pancreas is detected as ectopic adipocytes infiltrating the pancreatic tissue where fats deposit in adipocytes in the pancreatic tissue inducing pathological disorders such as insulin resistance and pancreatic cell injury and ultimately resulting in pancreatitis." (PMID 36915161, 2023). "Moreover, the FMDSS mice showed significantly higher blood glucose level, lower insulin secretion, more beta cell destruction and more signs of pancreatitis compared with the FMNC mice, even though all the recipient mice were provided pure water during the trial." (PMID 36978130, 2023). "However, because Pdx1-Cre recombination occurs in the whole pancreas, including in islet, acinar, and even pancreatic stem cells, β cells’ malfunction results in higher insulin and reduced blood glucose levels, both of which may exacerbate pancreatitis." (PMID 34314386, 2021). "However, given the evidence presented in the present study, it’s entirely possible that the beneficial effects of insulin therapy in HTG-induced pancreatitis patients may also be due to a direct protection of acinar cell injury." (PMID 34282152, 2021). "Dengue virus inducing a transient pancreatitis or insulin resistance could be a possible mechanism." (PMID 29078811, 2017). "Therefore, the aim of the current study was to test the protective effects of insulin on pancreatic acinar injury induced by bona fide pancreatitis-inducing agents, such as ethanol and ethanol/fatty acid metabolites, including palmitoleic acid ethylesters (POEE) and palmitoleic acid (POA)." (PMID 24993827, 2014). "Optimal outcomes depend on addressing precipitating factors, close monitoring of biochemical parameters, and multidisciplinary specialist involvement to coordinate insulin therapy, manage metabolic derangements, and prevent recurrence of DKA or pancreatitis." (PMID 41262426, 2025). "Pancreatitis had a similar prevalence among GLP-1RA and basal insulin users (3.3% vs 3.5%, although χ21 = 114.9 and P < .001 due to large numbers)." (PMID 38175642, 2024). "Various treatments have been proposed for managing pancreatitis due to HTG, including insulin infusions and plasmapheresis." (PMID 39429311, 2024). "Caerulein and palmitoleic acid (POA)/ethanol-induced pancreatitis was more severe in both Ins2Akita and PACIRKO vs control mice, suggesting that endogenous insulin directly protects acinar cells in vivo." (PMID 34282152, 2021). "Collectively, these data suggest that endogenous insulin directly protects pancreatic acinar cells during pancreatitis and deletion of acinar IRs, as is the case with PACIRKO mice, makes pancreatitis worse." (PMID 34282152, 2021). "Insulin and heparin can be used to increase LPL activity during the acute phase in patients with pancreatitis secondary to HTG." (PMID 31203594, 2019). "For severe cases of chylomicronemia (triglycerides > 500 mg/dL and abdominal pain or pancreatitis), inpatient therapy is preferred with NPO, intravenous hydration, low dose insulin and/or heparin infusions, and gradual advancement to a low-fat diet." (PMID 26925282, 2016). "Retrospective review of insulin monotherapy in patients with non-diabetic hypertriglyceridemic pancreatitis." (PMID 40432658, 2025).